CXCL9 (C-X-C motif chemokine ligand 9)
Diseases named in the same sentence as CXCL9 in open-access papers (continued):
Sharing a sentence is not in itself a finding about the gene and the disease.
tumor (continued). "Further studies are warranted for analysing the potential value of CCL5, CXCL9 and IFN-ɣ as biomarkers of response to trastuzumab-deruxtecan and the possible synergism between trastuzumab-deruxtecan and tumor-infiltrating NK cells." (PMID 38167224, 2024). "CXCR3 ligands, CXCL9/10/11, play important roles in the TME, that can both support and inhibit tumor growth." (PMID 38786066, 2024). "IT CXCL9/10-DC, in combination with ICB, overcomes resistance and establishes systemic tumor-specific immunity in murine models." (PMID 38518770, 2024). "Further strengthening these data, immunohistochemical and immunofluorescent analysis revealed an overall significant increase in the levels of CXCL9 and CXCL10 within the TME of mouse PDAC tumours upon IGF blockade." (PMID 39165364, 2024). "In the context of ICIs, these drugs are thought to act primarily on T cells, stimulating them to secrete IFN-γ, which in turn reduces endothelial VEGFA and increases the levels of CXCL-9, CXCL-10, and CXCL-11, contributing to tumor vascular normalization." (PMID 39850892, 2024). "CXCL9 and CXCL10 expression have been reported to contribute to the generation of a "hot" tumor microenvironment." (PMID 38226288, 2024). "The chemokines CXCL9, CXCL10, and CXCL11 are generally produced by activated macrophages and dendritic cells to facilitate CD8+ T cell infiltration to injured or tumor tissues." (PMID 39324134, 2024). "For CD8+ T cells to effectively infiltrate the tumor site, chemokine receptors, such as CXCR3, must interact with their corresponding chemokines (CXCL9, CXCL10 and CXCL11)." (PMID 39409972, 2024). "Our results showed that the expression of CXCL9, CXCL10, GZMA, GZMB, PRF1 and IFNG was significantly higher in tumor tissues than in adjacent normal tissues in GC patients." (PMID 39376571, 2024). "Collectively these results further highlight the role of CXCL9 and CXCL10 in potentiating, not only anti-tumor CD8+ T cells but also anti-tumor CD4+ T cells, including cytotoxic CD4+ T cells." (PMID 39474427, 2024). "HLA-DRA also showed a surprising positive correlation with CCL4, CCL5, CXCL9, and CXCL10, indicating its beneficial role in the human immune response through inducing immune cell infiltration and improving tumor clearance in the body." (PMID 38931345, 2024). "Cytokines CXCL9 and CXCL10, when released from tumor cells following irradiation, can drive T cell chemotaxis, facilitating their migration into the tumor microenvironment." (PMID 38323315, 2024). "CXCL9 was the only gene showing significant differential expression between p16+/HPV- and p16-/HPV- tumours being upregulated within the stromal compartment of the former." (PMID 39328208, 2024). "In the first set of experiments, a relatively low dose (50μg/mouse) of CXCL9-Fc or CXCL10-Fc was administered, starting 3 days after tumor engraftment." (PMID 39474427, 2024). "Key chemokines including CXCL9 and CXCL10 have been shown to attract CD8+ cytotoxic T cells to the tumor microenvironment." (PMID 38822345, 2024). "Chemokines can serve pro- or anti-tumor functions, with the chemokines CXCL9 and CXCL10, ligands for CXCR3, being of the most interest in the anti-tumor category due to their ability to attract effector CD8+ and CD4+ T cells." (PMID 38803496, 2024). "Comparing changes in absolute cytokine levels for IFNγ and the IFNγ-inducible cytokines CXCL9 and CXCL10 to the tumor-related cytokines EGF, HGF and VEGF highlights the strong treatment related effects for IFNγ-pathway related cytokines." (PMID 38454126, 2024). "Analysis of the MDMs demonstrated that IFNG neutralization diminished induction of CXCL9, CXCL10 and CXCL11 gene expression in MDMs in both tumor model systems." (PMID 39414902, 2024). "The CXCL9 and CXCL10/CXCR3 axes play two roles in the tumor environment: paracrine signaling for immune activation and autocrine signaling for cancer proliferation and metastasis." (PMID 38720340, 2024).
tumor (continued). "Tumor resident cDC1 is also the main producers of CXCL9 and CXCL10 chemokines that promote the recruitment of CD8 + T cells to the tumor microenvironment." (PMID 38231450, 2024). "IFNγ induces macrophages to produce more CXCL9 and CXCL10, two chemokines that bind to CXCR3 on the surface of T cells and promote their recruitment for anti-tumor immune response." (PMID 38787372, 2024). "For instance, CCR4/5 and CXCR3, expressed by CD8+ T cells, allow their ligands CCL5, CXCL9, and CXCL10 to guide the migration of CD8+ T cells into tumor tissue." (PMID 39769501, 2024). "Of note, one of these genes, CXCL9, which acts as a ligand of CXCR3, has been reported to have a controversial role in tumor initiation and progression, exhibiting both positive and negative prognostic values depending on the type of tumor." (PMID 38627854, 2024). "In tumor regions, the expression levels of CCL2, CCL5, CCL20, CXCL9, CXCL10, CXCL11 and CXCL12 were generally higher in hot tumors than in the other two groups." (PMID 37847338, 2024). "This NE-driven resistance to anti-PD-1 therapy can affect the secretion of C-X-C Motif Chemokine Ligand 9 (CXCL9) and adenosine (ADO) in tumor cells, thereby inhibiting chemotaxis and the function of CD8 T cells." (PMID 38892423, 2024). "This suggests differing tumor-intrinsic pathways are important for tumor growth control and local recruitment of CD8+ T cells, such as CXCL9/10 upregulation in TC5." (PMID 38727236, 2024). "An increase in PD1+CD8+ T cells, which has been shown to contain a pool of systemic tumor-specific T cells, and PD1+CD4+ T cells was also observed in response to CXCL9/10-DC, with the highest magnitude following combination therapy." (PMID 38518770, 2024). "Tregs are recruited by tumor tissues in the TME through a variety of chemokines, leading to Treg enrichment locally in the tumor (CCL17/22-CCR4, CCL5-CCR5, CCL1-CCR8, CCL28-CCR10 and CXCL9/10/11-CXCR3, etc.)." (PMID 39329710, 2024). "CXCL9 and CXCL10 (CXCL9/10) signal through C-X-C motif chemokine receptor 3 (CXCR3) to promote the tumor infiltration of CXCR3+ effector T cells, including type 1 T helper (Th1) cells and CD8+ cytotoxic T lymphocytes." (PMID 38518770, 2024). "In addition, IT CXCL9/10-DC enhances the relatively modest efficacy of PD-1/PD-L1 blockade in a Lkb1-deficient, Kras-mutant murine NSCLC model with high TMB, leading to the complete eradication of a subset of tumors and the establishment of tumor-specific immune memory." (PMID 38518770, 2024). "We implemented in situ hybridization to detect messenger ribonucleic acid (mRNA) transcripts of CXCL9, CXCL10, and IL-8 along with a synaptophysin immunohistochemical co-stain to identify tumor cells." (PMID 38822345, 2024). "PPARα agonist induced chemokine expression in the tumor (CXCL9/10) together with the respective receptor (CXCR3) on CD8+ T-cells, allowing their recruitment into the tumor tissue microenvironment." (PMID 37686465, 2023). "The expression of CXCL13 can also be epigenetically tuned by the combined application of the HDACi entinostat with tumor-targeted delivery of interleukin-12 (IL-12), which achieved an elevated level of CXCL13 and CXCL9." (PMID 38044445, 2023). "In BC cells, hypoxia induces the expression of BIRC2, which counters the capability of CXCL9 to recruit CD8+ T cells and NK cells to the tumor, and hence increases tumor growth and resistance to anti-PD-1 therapy." (PMID 36834641, 2023). "For example, cDC1s are the main secretory cells of C-X-C motif chemokine ligand 9 (CXCL9) and CXCL10 in TME, which promote infiltration of CD8+ T cells into the TME and maintain effector T cells at the tumor site for long periods." (PMID 37876967, 2023). "Blocking ATX activity changed the phenotype of the mice by decreasing the plasma concentrations of CXCL9, CXCL10, and CCl2 and the tumor concentrations of LIF, TGFβ1, TGFβ2, and prolactin." (PMID 37296899, 2023).
tumor (continued). "The CXCL9, -10, -11/CXCR3 axis regulates immune cell migration and activation, including that of CTLs and NK cells, which inhibit tumor development." (PMID 37777634, 2023). "IL11 mutein competitively inhibit IL11 to upregulate CXCL9 and MHC-I in tumor and attenuated tumor growth." (PMID 37365574, 2023). "In the treated group, the LIVP-RFP cytokine analysis suggested elevation of CXCL10 in the tumor samples and IFN-α, IFN-γ, CCL2, CCL3, CXCL9, and CXCL10 in the sera samples." (PMID 37112810, 2023). "Olaparib and atezolimumab (anti-PD-L1) increased IFNγ, TNFα, and CXCL9/CXCL10 expression and tumor infiltration by lymphocytes." (PMID 36831435, 2023). "CXCL9 and CXCL11 are key chemokines for the trafficking of effector T cells into the tumour and are secreted by macrophages and stromal cells in response to IFN-γ secreted by T-cells." (PMID 37013636, 2023). "Current monoculture tumor spheroid models lack the presence of specific cytokines present in the PDAC TIME, such as CCL4/MIP-1β, CCL5/RANTES, CXCL9, and CXCL10 accidentally simulating an immune silent or excluded PDAC TIME." (PMID 37519820, 2023). "These DCs, along with macrophages and tumor cells, secrete chemokines like CXCL9 and CXCL10, which aid in recruiting circulating CXCR3-expressing CD8+ T cells to the tumor site to exert cytotoxic effects on tumor cells." (PMID 37920470, 2023). "Western blot data also indicated that cytokines content in the tumor was remarkably increased after combined therapy compared with other groups, including IL-12, IFN-γ, CXCL-9, and CXCL-10." (PMID 37391451, 2023). "This demonstrated significantly higher expression of CXCL9 and CXCL10 for the anti-tumor immune-suppressive M2 tumor-related macrophage family than for the M1 macrophage (p = 6 × 10−27, 8 × 10−6, respectively)." (PMID 37686653, 2023). "A recent study showed that CXCL9 and CXCL10 from macrophages are critical for the recruitment of T cells in the tumor microenvironment." (PMID 36978108, 2023). "In practice, literature has indicated that RT enhances the homing rate of immune cells to the tumor microenvironment that is stimulated by IFNs and ISG CXCL9/10." (PMID 36688994, 2023). "When overlaying gene expression of CXCL9, CD3D (t cells) and CD68 (macrophages), we see moderate spatial correlation with CXCL9 and CD3D (r = 0.4, p = 3E-29) along the tumor-stromal interface, and weaker correlation with CD68 (r = 0.17, p = 1E-10)." (PMID 36906603, 2023). "Studies have shown that CXCL9 and CXCL10 can directly recruit CD4+ and CD8+ T cells, and NK cells to the tumor site in various cancers." (PMID 38104126, 2023). "In cutaneous melanoma mouse models, temozolomide increased the expression of CCL5, CXCL9, and CXCL10, resulting in increased T-cell trafficking to the tumor." (PMID 36949946, 2023). "Previous studies have shown that chemokines CXCL9 and CXCL10 can recruit CD8+ T cells, Th1 cells and NK cells by recognizing CXCR3 signals, thus triggering anti-tumor response." (PMID 37950246, 2023). "The CXCL9 involved signaling axis (CXCL9, -10, -11/CXCR3) was found to suppress tumor progression by regulating immune cell migration, differentiation, and activation and further promoting anti-tumor immune response." (PMID 37926766, 2023). "This correlated with an upregulation of the chemokines CCL5, CCL19, CXCL9, and CXCL10 expression from the tumor." (PMID 38022679, 2023). "Elevated levels of CXCL9 correlate with increased tumor infiltration of CD8+ T cells and tumor suppression." (PMID 37046739, 2023). "NLRC3 showed moderate and strong correlations with CCL5, CXCL9, CXCL10, CXCL11, CXCR3, and CCR5, resulting in an increased recruitment of NK cells, TH1 cells, and CD8+ T cells in tumor tissues." (PMID 36808166, 2023). "CXCL9, CXCL10, and CXCL11 were expressed most prominently by cluster 11, which was annotated as CD14(+) monocytes derived from neoplasms." (PMID 37686653, 2023).
tumor (continued). "In tumor-bearing mice, CAR T cells modified with CXCL9 displayed enhanced infiltration of immune cells by attracting a greater number of T cells to the tumor site." (PMID 37926766, 2023). "Surprisingly, expression of IL-12, IFN-γ, CXCL-9, and CXCL-10 in tumor center was dramatically decreased than tumor periphery." (PMID 37391451, 2023). "ELISA measurements in B7H4 staining positive tumours: IL-9, IL-18, IP-10(CXCL10), MIG (CXCL9) and SDF-1a (CXCL12)." (PMID 36980202, 2023). "Using a machine learning mechanism that allows for a combined score across 7 tumor histotypes, a score with 11 variables has been created, highlighting that TMB and CXCL9 are the main predictors for all cancers considered." (PMID 36900006, 2023). "Specifically, interferon-gamma (IFN-γ) and its induced production of CXCL9 and CXCL10 contribute to the establishment of an inflammatory tumor microenvironment, which plays a role in the tumor’s response to ICIs therapy." (PMID 37835371, 2023). "The CXCL9, 10, and 11/CXCR3 chemokine axis has been increasingly recognized as an important regulator of the tumor microenvironment." (PMID 37686653, 2023). "M1 macrophages exhibit enhanced antigen-presenting activity while secreting CXCR3 ligands (CXCL9, CXCL10, CXCL11) and CXCL16 to recruit Th1 and NK cells and secrete TNF-α, synergistically exerting anti-tumor functions." (PMID 37063892, 2023). "GSK126 played a vital role in promoting IFN-γ, which increased CXCL9 and CXCL10 expression in the tumor, promoting T cell proliferation, maturation, activation, and chemotaxis into GBM, thereby inhibiting tumor growth and prolonging survival." (PMID 38104126, 2023). "The addition of TIGIT blockade to MWA resulted in the up-regulation of CXCL9 and CXCL10 expression in TAMs and their receptor CXCR3 expression in T cells, which restrain tumor growth and enhance anti-tumor immunity." (PMID 36900218, 2023). "LIF has immunosuppressive functions in some tumour contexts, in part by repressing CXCL9 (also part of the IPASS) and CD8+ T-cell infiltration of tumours." (PMID 37013636, 2023). "Tumor-localized IL9 also polarized TAMs toward M1 in vivo and made them release CCL3/4 and CXCL9/10 to recruit antitumor immune cells, including T and natural killer cells, into the tumor microenvironment." (PMID 36968220, 2023). "On the contrary, M1 TAMs produce proinflammatory cytokines, such as TNF and IL-12; recruit Th1 CD4+ T cells through CXCL9 and CXCL10 secretion; and induce direct tumor cell killing." (PMID 37377970, 2023). "Treg cells are mainly recruited to the tumor microenvironment by chemokines such as CCL1, CCL17, CCL22, CCL28, CXCL9, CXCL10, and CXCL11." (PMID 37686093, 2023). "We investigated associations of a 4-chemokine expression signature (c-Score: CCL4, CCL5, CXCL9, CXCL10) with metrics of antitumor immunity across tumor types." (PMID 37558751, 2023). "The cGAS-STING pathway mediates induction of CXCL9/10 in DCs; therefore, STING agonists are potential as therapeutic agents for activating DCs and recruiting T lymphocytes in tumor treatment." (PMID 36688994, 2023). "Protein levels of CXCL9 and CXCL10 were markedly higher in tumor-bearing brains after T-αFGL2 treatment compared to T-Ctr treatment." (PMID 36759517, 2023). "As a result, CXCL9 and ten from dendritic cells anchor CTLs to the vascular endothelium via CXCR3 in the bloodstream, effectively inducing CTL infiltration into the tumor." (PMID 37046727, 2023). "CXCL9 and CXCL10 can be generated by antigen-presenting cells (dendritic cells and macrophages) and by tumor cells." (PMID 37063837, 2023). "Upregulation of several chemokines, including CCL3, CCL5, CCL22, CXCL9, CXCL10, and CXCL11, has been described to play different roles with effects depending on tumor type and other TME factors." (PMID 36831435, 2023). "We found that a significant gradient toward the serum (CXCL9, IL6, IL10, IL13) or the tumor tissue (IL1B) exists for all cytokines in question." (PMID 36980700, 2023).
tumor (continued). "CD4+ T-cell activation (via tumor-specific MHC II) leads to increased interferon-gamma (IFN-γ) secretion, thus enhancing CXCL9 production and PD-L1 expression, culminating in an immunotherapy-sensitive tumor phenotype." (PMID 37761972, 2023). "Preclinical modeling has demonstrated its importance in recruiting CD8+ T cells to the tumor microenvironment via CCL5, CXCL9, and CDCL10 chemokine release." (PMID 37903733, 2023). "The CXCL9- and CXCL11-expressing cell lines significantly suppressed tumor growth on day 11 post-inoculation compared to that by the Vector, and this suppression was observed until day 18 (p < 0.05)." (PMID 37218983, 2023). "Namely, epigenetic reprogramming of chemokine expression has been reported upon treatment with DNMTi, EZH2i and LSD1, increasing tumor production of CXCL9 and CXCL10 chemokines, known to be involved in T cell recruitment to the tumor." (PMID 37090711, 2023). "CXCL9 induced by IFN-γ primarily mediates lymphocyte infiltration into lesions and inhibits tumor growth." (PMID 37046739, 2023). "The repression of AT3 tumor growth was accompanied by increases in STAT-1 signaling, the expression of STAT-1 target genes, such as Cxcl9 and Cd274, the recruitment of T cells, and the re-sensitization of otherwise resistant AT3 tumors to PD-1 immunotherapy." (PMID 37500611, 2023). "In turn, the IL9-polarized macrophages secreted chemokines, including CCL3, CCL4, CXCL9, and CXCL10, to recruit antitumor T cells, NKs, DCs, and macrophages to infiltrate the tumor." (PMID 36968220, 2023). "Chemo-taxis of effector T cells to the tumor depends on the expression of CXCR3 on T cells and the presence of its ligands, CXCL9, CXCL10, and CXCL11 within the TIME." (PMID 37377970, 2023). "CXCL9 and CXCL10 can recruited TH1 cells and NK cells into the tumors and played a role in tumor inhibition." (PMID 38125697, 2023). "In order to investigate the role of β-catenin in the regulation of CXCL9 and ADO secretion by NE, we transfected tumour cells with β-catenin-shRNA lentivirus or scramble-shRNA lentivirus (NC)." (PMID 36646807, 2023). "Pre-treatment with oxaliplatin and cyclophosphamide induced a pro-inflammatory tumor microenvironment and enhanced secretion of CCL5, CXCL9, CXCL10, and CXCL16 by tumor-infiltrating macrophages, leading to enhanced ROR1-CAR-T cell infiltration." (PMID 36949946, 2023). "Eosinophil commitment to Th1 response was previously shown as well where these leukocytes produced CXCL9, CXCL10, CXCL11, and CCL5 under the effect of TNF-α and IFN-γ, which recruit T and NK cells to eradicate tumor." (PMID 37587450, 2023). "To demonstrate the role of WNT7A in the regulation of CXCL9 and ADO secretion by NE in tumour cells, we transfected tumour cells with WNT7A-shRNA lentivirus or scramble-shRNA lentivirus (NC)." (PMID 36646807, 2023). "Similar to NPTyr-C9Ap, NPSur-C9AP was supposed to deliver pSur-C9AP into both tumor cells and other normal cells, but the Sur promoter of pSur-C9AP would only drive the coexpression of CXCL9 and αPD-L1 specifically in tumor cells." (PMID 37031188, 2023). "CXCL9, CXCL10, and CXCL11 are ligands of CXCR3 and have been increasingly recognized as key regulators of the tumor microenvironment." (PMID 37686653, 2023). "More recently, however, the same CXCL9, 10, and 11/CXCR3 axis has also been shown to have paradoxically a pro-tumor effect as well, whereby in an autocrine signaling fashion, it increases tumor cell proliferation, angiogenesis, and metastasis." (PMID 37686653, 2023). "In order to further study the mechanism of NE-induced changes of CXCL9 and ADO secretion in tumour cells, we used transcriptome sequencing to detect gene expression levels in A549 cells after NE stimulation." (PMID 36646807, 2023). "As part of the chemokine superfamily, CXCL9, in collaboration with CXCR3, activates an immune response in the tumor microenvironment to fight cancer." (PMID 37240946, 2023).